IL6 (interleukin 6)
Diseases named in the same sentence as IL6 in open-access papers (continued):
Sharing a sentence is not in itself a finding about the gene and the disease.
infection (continued). "At 5 days after the infection, the virus titer was significantly decreased as was the amount of produced IL-6 in the lung tissue, the number of total cells in the bronchoalveolar lavage fluid was reduced by the LG2055 administration." (PMID 24717726, 2014). "The increased number of intestinal granulomas in IL-6−/− mice also indicated potentiation of type 2 responses early in infection, as these are foci of alternatively activated macrophages, which form in an IL-4Rα-dependent manner." (PMID 24185641, 2014). "Mean IL-6 and GRO-γ levels decreased over the course of infection, and the decrease was statistically significant in the case of IL-6 (p ≤ 0.05)." (PMID 25398383, 2014). "Of the 305 cases, they reported the presence of bacteria in 30 AF samples, 26 of which they attributed to infection based upon elevated levels of interleukin-6 (IL-6) (>11.2 ng/mL) and 4 of which were deemed “colonizers” due to levels of IL-6 <2.6 ng/mL." (PMID 25505898, 2014). "Similar to the mRNA expression, protein levels of IL-1β, TNF, IL-6, IFNγ, and IL-1α were also significantly elevated in the brains of db/db mice when compared to WT mice at day 8 after infection as measured by the multiplex immunoassay (P <0.05)." (PMID 24750819, 2014). "In our mice experiment, we found IL-6 significantly increased not only in the early but also in the late stage of infection." (PMID 24725777, 2014). "In line with this we observed increased expression of the proinflammatory cytokines IL-6 and TNFα peaking at day 3 or 5 post infection, respectively, and subsiding at day 7 after the infection." (PMID 24918427, 2014). "Irrespective of the genotype of mice, IL-6 and IFN-γ serum levels, splenic TNF-α and IFN-γ as well as hepatic TNF-α and IL-6 concentrations increased multifold until day 7 following infection." (PMID 24932221, 2014). "Serum levels of TNF-α and IL-6 from the WT-infected mice decreased at 9 h post-infection, remained at high levels, and returned to basal levels at 12 h post-infection." (PMID 25264876, 2014). "In the mouse model, we detected strong increased levels of the pro-inflammatory cytokines TNFα and IL-6 in the brain during early infection, which coincided with a massive increase in C. glabrata cell number in this organ." (PMID 25356907, 2014). "The significantly higher concentrations of IL-6 in lung tissues were observed mainly in the early stage of infection (mostly at 4 dpi)." (PMID 24846450, 2014). "We measured pro-inflammatory cytokine response (TNF-α, IFN-γ, IL-1β, and IL-6) in the lungs of untreated or EtOH-treated mice and uninfected or infected with Ab at 4, 24, 48, and 72 h post-infection." (PMID 24752133, 2014). "We examined the levels of TNF-α, IFN-γ, IL-1β, and IL-6 in the kidneys of untreated or EtOH-treated mice and uninfected or infected with Ab at 72 h post-infection." (PMID 24752133, 2014). "Inflammation and infection also induce interleukin (IL)-6 or IL-22, which can upregulate hepcidin through the phosphorylation of STAT3." (PMID 24910614, 2014). "While mice were infected with a lower dose of ΔspxA2 in colonization and competitive infection assays, low levels of IL-6 production would be beneficial for the mice to clear infection, thus lead to reduced ΔspxA2 recovered from the tissues." (PMID 25264876, 2014). "In particular, the CSF levels of IL-6 were shown to be closely correlated with clinical severity in EV-A71 patients and a neonatal mouse model of infection." (PMID 25412347, 2014). "Preterm fetal membranes with active infection treated with silibinin showed a decrease in IL-6, IL-8 and MMP-9 expression." (PMID 24647589, 2014). "In this study, we examined the contribution of IL-6 to the inflammatory and immunoregulatory response generated following infection with the Th2-cell and Treg-cell-inducing gastrointestinal helminth Heligmosomoides polygyrus." (PMID 24185641, 2014).
infection (continued). "Of note, the expression of IL6 was significantly down regulated by infection with Mtb-H (Supplement S2)." (PMID 24743303, 2014). "Several studies have shown that cocaine directly suppresses production of IL-6 in the blood during acute infection, but little is known of how cocaine-dependent individuals (CDIs) respond to cues signaling infection." (PMID 24090796, 2014). "Infection of HIBCPP cells with a PorB-deficient mutant of the MC58 strain for 4 h resulted in a stimulation of nfkbiz and il6 comparable to the PorB-containing strains." (PMID 25347003, 2014). "Inflammation is a natural response to damage and/or infection that are mediated by pro-inflammatory cytokines including interleukin 1 beta (IL-1β), interleukin 6 (IL-6), and tumor necrosis factor alpha (TNFα)." (PMID 25228881, 2014). "Hepcidin, which is upregulated by increased levels of serum iron and by inflammatory cytokines such as IL-6, is induced by Plasmodium blood-stage infection and was indeed shown to inhibit concomitant development of superinfecting liver stages." (PMID 25257508, 2014). "Depletion of SSH1 mRNA by the two SSH1-specific siRNA duplexes resulted in significantly impaired IL-8 and IL-6 production 6 h post infection with the invasive S. flexneri strain M90T." (PMID 25187968, 2014). "We evaluated the levels of TNF-α, IFN-γ, IL-1β, and IL-6 in the hepatic tissue of untreated or EtOH-treated mice and uninfected or infected with Ab at 24, 48, and 72 h post-infection." (PMID 24752133, 2014). "EtOH and Ab-infected animals demonstrated lower IL-6 levels than EtOH-treated animals (P<0.05) 24 h post-infection." (PMID 24752133, 2014). "Urinary IL-6 was positively correlated to and IL-10 was negatively correlated to infection intensity and urinary tract inflammation in S. haematobium-infected children." (PMID 25223302, 2014). "In the case of infection with Candida hyphae, a reduction in IL-6 production was observed when NT5C3 was knocked down; however, the results were not significant (P-value = 0.1858) (data not shown)." (PMID 25147207, 2014). "At day 2 post-infection, the virus provoked a significant increase on the levels of transcription of IL-6, CK10 and TLR3." (PMID 25333488, 2014). "In this study, we found that infection with viable S. oralis or exposure to H2O2 induced IL-6 production in Detroit 562 epithelial cells." (PMID 24498253, 2014). "We measured concentrations of TNF-α, IFN-γ, MCP-1, IL-6, IL-10 and IL-12p70 in plasma of Asc−/−, Nlrp3−/− and WT mice 2 and 5 days after infection." (PMID 25115174, 2014). "As a major proinflammatory cytokine, Interleukin-6 (IL-6) takes part in the protection from pathogens infection." (PMID 24772425, 2014). "In fact, interleukin-6 is a cytokine not only involved in inflammation and infection responses but also in the regulation of metabolic, regenerative, and neural processes." (PMID 24729890, 2014). "Three hours post-infection, a significant increase in KC, IL-1β, TNFα, and IL-6 levels was detected in BALs from TLR9-/- compared to WT mice." (PMID 24595157, 2014). "During the late phase of the infection (72 hours) most mediator levels were higher in TMpro/pro mice when compared with WT mice, significantly so for lung IL-12p70 and IL-6 concentrations." (PMID 24762740, 2014). "As IL-6 has been proposed to play a role in cell survival in other damage and infection models, we evaluated the effects of anti-IL-6 mAb on epithelial cell death in these experiments." (PMID 25478789, 2014). "IL-6 induction was highest in A549 cells at 10 h of infection, while it was highest at 24 h of infection in BEAS-2B and NHBE cells." (PMID 25313647, 2014). "IL-6 production increased in TS mice with the course of the infection when 50 cysts were used; TR mice presented similar low levels of this cytokine." (PMID 25437299, 2014).
infection (continued). "Interleukin-6 (IL-6) is a proinflammatory cytokine produced by monocytes and macrophages during trauma, infection, and stress that instigate acute-phase protein production and inflammation." (PMID 25025081, 2014). "In order to characterize the effect of immunization with the inactivated LPS deficient vaccine on cytokine levels, sera were collected from vaccinated and control mice 12 h post-infection and the levels of IL-1β, IL-6 and TNF-α were determined." (PMID 25485716, 2014). "Between 14 h and 48 h post infection, IL-6, IL-8, MCP-1, GROα (NS), Rantes (NS) synthesis and the parasite burden (NS) increased." (PMID 24886982, 2014). "High levels of IL-6 in a neonatal mouse model upon EV-A71 infection were shown to result in severe tissue damage and eventual death." (PMID 25412347, 2014). "In this sense, it was found that humans infected with TcI strains produce higher levels of the cytokine IL-6, whereas infection with TcII strains induces more IL-1 and IL-17 production." (PMID 25371910, 2014). "At 48 h post-infection, culture supernatants and cell lysates were collected for measurements of the virus titer and IL-6 levels." (PMID 25412347, 2014). "NHBE cells showed no significant change in antiviral gene response, and in IFN-β and IL-6 expression at 10 h infection." (PMID 25313647, 2014). "The ability of Giardia sp. to modulate IL-6 during in vivo infection remains incompletely understood." (PMID 25289678, 2014). "Consistent with this, TNFαand IL-6 secretion by F. tularensis-infected MDMs declined over the first 3 hours of infection, whereas cytokine secretion by F. novicida-infected MDMs increased at least 30-fold over this same time period." (PMID 25295729, 2014). "The role of miR-146a in regulating NF-κB activation was consistent with the observed defect in downregulation of NF-κB-dependent cytokines and chemokines IL-1β, IL-6, Cxcl1 and Cxcl2, in B6 miR-146a−/− mice at 4 weeks post-infection." (PMID 24967703, 2014). "This gains further strength after detection of higher levels of pro-inflammatory cytokines such as IFN-γ and TNF-α and lower level of pleiotropic cytokine IL-6 in these mice during the initial stage of infection." (PMID 25437299, 2014). "The earliest cytokine noted was IL-6, which increased at 2 days, then dropped to control level at 6 days post infection." (PMID 24725777, 2014). "Secretion of IL-6 started at 6 h post infection for all stimuli with a continuous increase over 48 h." (PMID 25488836, 2014). "The cells with depletion of EOLA1 were treated with LPS (100 ng/ml) at the point of 48 h infection and IL6 was detected by ELISA assay 24 h after LPS induced." (PMID 24916366, 2014). "IL-1β and IL-6 were then showing up, presumably to sustain the inflammatory response, with a ‘mirror’ image of their respective increase all along infection." (PMID 24637903, 2014). "Consistent with the cytokine levels detected in the serum during infection, splenocytes from Ity3.RecG presented significant lower levels of IL-6 after stimulation with LPS and flagellin." (PMID 24505352, 2014). "HBV replication tends to increase after 3–4 days following infection when the IL-6 level has already returned to baseline and remains stable afterward." (PMID 24618592, 2014). "Cases with congenital malformation, ascending infection, and perinatal anoxia showed increased IL-6, CRP, and TNF-α, respectively." (PMID 24659848, 2014). "We found that peripheral monocytes recognized the presence of live GC-FA19 infection and robustly responded by releasing cytokines IL-6 and TNFα as well as the antibacterial lipocalin NGAL, and by upregulating hepcidin gene expression." (PMID 24489950, 2014). "A time of addition study, analysing the ability of neutralising IL-6 antibodies to block HCMV reactivation following stimulation with LPS, revealed that the effects of IL-6 signalling must manifest at immediate-early times post infection." (PMID 24945302, 2014).
infection (continued). "In a separate study, IL-6, TNFα, IL-8, and IL-15 were significantly higher in the group with severe pH1N1 infection when a panel of nine serum cytokines was analyzed." (PMID 25003343, 2014). "IL-6 is a proinflammatory cytokine of innate immunity, which is secreted by T cells and macrophages to stimulate immune responses during infection." (PMID 25003343, 2014). "In a significant number of neonates with EONS, infection starts in utero resulting in elevated levels of IL-6 and IL-8 in cord blood." (PMID 25485809, 2014). "The present study reports for the first time the relationship between urinary cytokines IL-6, IFN-γ, TNF-α and IL-10, and S. haematobium infection and infection-associated urinary tract pathology in primary school children." (PMID 25223302, 2014). "At 24 h post infection, IL-6 increased significantly whereas IL-8 remained at a low level compared to 8 h." (PMID 24886982, 2014). "Only one study found lower CRP levels in malnourished than well-nourished children with similar infections, despite higher levels of IL-6." (PMID 25153531, 2014). "IL-6 and eotaxin-1 expression peaked at day 7 pi, whereas G-CSF initially peaked on day 5 but remained high throughout infection." (PMID 24699832, 2014). "IL-6 is an inflammatory cytokine that is secreted by leukocytes and other various cell types during infection." (PMID 25540075, 2014). "A significant induction of il6 after challenge with MC58siaD− was observed firstly after 4 h and secretion of IL6 protein was detectable even later after 8 h of infection." (PMID 25347003, 2014). "IL-6 is a cytokine that shows early response to infection, preceding the increase in C-reactive protein and followed by TNF-α release." (PMID 25614712, 2014). "At 24 and 48 hpi, RRV infection of OA hOBs elicited consistently lower levels of IL-6 transcription compared to healthy hOBs, but its expression was increased at 96 hpi." (PMID 25407789, 2014). "B6 miR-146a−/− mice contained higher levels of IL-6 at 4 weeks post-infection, compared to wild-type, consistent with observations in joint tissue." (PMID 24967703, 2014). "The production of IL-6 and IL-8 in uninfected cells was often high, and in some donors infection led to a decrease in cytokine production." (PMID 24450835, 2014). "In the group of patients with a secondary infection, IL-6 levels were slightly lower than in the primary infection group, but no statistical difference was observed between the two groups." (PMID 25295285, 2014). "IL-6 has both pro- and anti-inflammatory actions, and is a major mediator of the brain's immune response to trauma or infection." (PMID 24914808, 2014). "Particularly, in Sm111-infected mice, Fe levels were positively correlated to all considered markers of infection, while Se levels correlated with bacterial load (p<0.001), IL-6 (p<0.05), and MIP-2 (p<0.001) concentrations." (PMID 24586389, 2014). "Infection with C. rodentium produced significant increases in the hepatic mRNA expression of TNFα, IL6, IL1β, serum amyloid A (SAA), and serum amyloid P (SAP), indicative of a hepatic inflammatory response." (PMID 24707356, 2014). "Acute phase responses is induced by infection or trauma, and mediated by cytokines like IL-6 and TNF-α." (PMID 25153531, 2014). "Together with the Treg cell-intrinsic negative IL-21R−/− signaling observed in WT:IL-21R−/− mixed BM chimeras, these data suggest that IL-21 restricted the virus-driven Treg cell expansion in LCMV-DOC infection independently of IL-6 signaling." (PMID 23696736, 2013). "Our results show that IL-6 shows high specificity in confirming infection and is 100% sensitive to predict mortality at 48 hours after antibiotics." (PMID 23869218, 2013). "The responses of BDCA1+ mDCs from different donors varied upon EV1 infection, with part (∼60%) of the donors inducing high levels of IL-6 and TNF-α, whereas the other donors responded poorly or produced no pro-inflammatory cytokines at all upon EV1 infection." (PMID 23638101, 2013).
infection (continued). "Infection increased the levels of pro-inflammatory cytokines IL-6 and IFN-γ in WT mice and as well IL-1β in Nlrp3−/− mice." (PMID 24312491, 2013). "The cytokines expression profile between K. rhinoscleromatis and K. pneumoniae infections shows minor differences in expression of IL-1β, IL-6 and IL-17, when similar infection kinetics is used." (PMID 23554169, 2013). "The highest fold change of IL-6 was the overall highest increase of all immune parameters that were measured and was detected 1 day post infection (x = 816.75 ± 353.14)." (PMID 24391635, 2013). "Interleukin 6 (IL-6) is a cytokine known to be part of the acute phase response, i.e. the initial immune system reaction to infection or trauma." (PMID 23938060, 2013). "IL1, produced in response to infection or tissue injury results in activation of NF-κB and downstream targets IL6 and IL8." (PMID 23799116, 2013). "On day 1 after infection, the levels of IL-6 in offspring mice exposed to methamidophos at 10 and 20 ppm were significantly decreased to approximately 66% (P < 0.05) and 50% (P < 0.01), respectively, of the control." (PMID 24369005, 2013). "The phenotype of these mice was confirmed by diminished IL-6 expression following infection of macrophages in vitro." (PMID 24339776, 2013). "In vivo, TNFα contributes to monocyte maturation after recruitment, whereas IL-6 supports the transition between the early stages of the infection and the sustained mononuclear influx into the infected gastric mucosa." (PMID 23970881, 2013). "At 20 weeks post-infection, lung tumors in KrasG12D; IL-6-/- mice were modestly smaller and less dense than those in KrasG12D mice." (PMID 24260500, 2013). "Upon infection, the serum IL-6 levels increased gradually and were significantly elevated above preinfection levels (P < 0.05) with highest levels of 13.7 pg/mL attained on 21 dpi." (PMID 24194772, 2013). "Several reports have also shown that a variety of proinflammatory cytokines can overcome Treg suppression during infection or in an inflamed environment, including IL-2, IL-4, IL-6, and TNF-α." (PMID 23593527, 2013). "After infection with M. tuberculosis, Il-6 mRNA levels were strikingly increased in lungs from Socs3fl/fl LysM cre mice when compared to littermates." (PMID 23853585, 2013). "From these, 3 cytokines (TNF-α, IL-6, and KC) were already elevated early at 1 hour after infection and remained elevated at 17 and 48 hours after infection." (PMID 23520553, 2013). "In fact, in vitro infection of IFN-γ-stimulated BMDMs demonstrated that CYLD inhibited activity of NF-κB resulting in reduced IL-6 production, ROS synthesis, and bacterial killing, which were all dependent on NF-κB." (PMID 23825949, 2013). "The Th17 pathway is commonly activated during infection with extracellular bacteria through cytokines, including IL-6, involved in differentiating naïve T cells into Th17 cells." (PMID 23378722, 2013). "In the C57BL/6J mice, an infection-dependent rise in Il6 mRNA was observed somewhat later (t = 48 h)." (PMID 24341411, 2013). "In our study secretion of TNF-α and IL-1β were also positively correlated with IL-6 in addition to IL-12, after 24 hours of infection." (PMID 23667550, 2013). "Similar results were observed from Ki67 staining in lung sections from KrasG12D and KrasG12D; IL-6-/- mice 28 weeks post-infection with adeno-Cre." (PMID 24260500, 2013). "rhodesiense human infections, abnormally high CSF IL-6 and IL-10 were observed, decreasing only after treatment indicative of potential for use in staging and treatment monitoring." (PMID 24194772, 2013). "We also observed that treatment with IL-10 significantly inhibited the expression of TNF-α and IL-6 induced by infection." (PMID 24260222, 2013). "Intriguingly, IL-6 and IL-11 transcripts were up-regulated over 30-fold correlating positively with both infection readouts." (PMID 23865616, 2013).